DHX9 (DExH-box helicase 9)
Diseases named in the same sentence as DHX9 in open-access papers (continued):
Sharing a sentence is not in itself a finding about the gene and the disease.
tumor (continued). "Additionally, multivariate analysis exhibited that DHX9 high level (p = 0.045), tumor size (p = 0.043), and vascular invasion (p = 0.038) were the independent adverse prognostic factors." (PMID 34676915, 2021). "On the contrary, others suggested that DHX9 acted as a tumor suppressor." (PMID 34676915, 2021). "Prognosis of the HCC patients was obviously correlated with tumor size (p = 0.011), differentiation degree (p = 0.047), lymph node metastasis (p = 0.004), vascular invasion (p = 0.0001), metastasis (p = 0.003), and DHX9 expression level (p = 0.032) in univariate analysis." (PMID 34676915, 2021). "It provided an insightful mechanistic view how genotoxic stress-impaired DHX9 may help tumor cells escape from genotoxic stress through promoting oncogenic circRNA expression." (PMID 32187976, 2020). "Furthermore, studies have demonstrated that DHX9 suppression exhibits lethality in most tumor cell types while causing no obvious detrimental effects on normal cells and organs, highlighting the feasibility of DHX9 as a therapeutic target." (PMID 40659605, 2025). "During tumor treatment, DHX9 expression changes may serve as a stress response." (PMID 40290118, 2025). "Importantly, the tumor-suppressive effect of DHX9 knockdown was reversed by BECN1 downregulation." (PMID 40659605, 2025). "Notably, DHX9 knockdown in melanoma reduced tumor progression." (PMID 39940956, 2025). "Finally, in high-grade MDS, overexpression of DHX9, on the one hand, may promote excessive proliferation, and on the other hand, may produce apoptotic resistance to exogenous anti-tumor agents." (PMID 37305700, 2023). "However, under pathological conditions, DHX9 may also be involved in tumor cell survival in various tumor types." (PMID 38275375, 2023). "Moreover, PDAC patients with higher DHX9 expression were significantly correlated with poorer survival and earlier recurrence, and DHX9 expression in PDAC was verified as an independent risk indicator for tumor recurrence and survival." (PMID 36578944, 2022). "In addition to the role of DNA replication, genomic stability, and transcription, the DHX9 may also participate in the shaping of the tumor microenvironment." (PMID 36578944, 2022). "Overexpression of DHX9 could rescue MCM2 or MCM3 knockdown-induced tumor inhibition." (PMID 28460433, 2017). "In conclusion, this study identifies RP11-439C15.4 as a tumor suppressor and elucidates the regulatory mechanism of the RP11-439C15.4/DHX9 axis in HCC, providing valuable insights into the mechanisms of HCC progression and potential therapeutic targets." (PMID 40677007, 2025). "lncRNA-SH3PXD2A-AS1 interacted with DHX9 to enhance FOXM1 expression, promote tumor cell proliferation, and accelerate cell cycle progression; lncRNA-KIMAT1 binds to and stabilizes DHX9, this effect is attributable to proteasomal degradation." (PMID 37048101, 2023). "Mechanically, SH3PXD2A-AS1 interacted with DHX9 to enhance FOXM1 expression, promote tumour cell proliferation and accelerate cell cycle progression." (PMID 35410446, 2022). "We firstly analyzed the expression of DHX9 in 369 cases of HCC and 50 cases of non‐tumor liver tissues based on TCGA database, and found that the expression of DHX9 in HCC was significantly higher than that in non‐tumor tissues." (PMID 34676915, 2021). "In summary, three genes in the PRG model (CASP1, CHMP6, and GZMA) is shown to be a protective factor, while the other three genes (CASP4, DHX9, and DFNA5) were defined as tumor-promoting factors." (PMID 34820372, 2021). "Additionally, histological analysis in the tumor xenograft tissue sections showed elevated levels of LC3, BECN1 and reduced p62 levels in the DHX9- knockdown group." (PMID 40659605, 2025). "And the tumor-suppressive effects of DHX9 silencing mediated by BECN1 is also not entirely autophagy-dependent." (PMID 40659605, 2025).
tumor (continued). "Previous studies have shown that DHX9 is essential for the survival of tumor cells, and inhibiting DHX9 results in fatal damage to tumor cells without affecting the function of normal cells." (PMID 36377508, 2023). "In addition, DHX9 KO hampered the promotion of cell growth by ectopic HIF1A-As2, indicating that the interaction with DHX9 is important for HIF1A-As2-promoted tumor growth." (PMID 37041291, 2023). "In addition, we showed that GSCAR activates the self-renewal ability of GSCs by mediating DHX9 and IGF2BP2 complex formation, leading to the stabilization of the SOX2 transcript and tumor growth." (PMID 37063420, 2023). "In addition, increased NUSAP1 and DHX9 mRNA levels were significantly correlated with higher tumor Gleason scores, while increased ILF2 were less correlated with tumor Gleason scores." (PMID 37047232, 2023). "Collectively, TRIM25 binds with DHX9 and DDX5 to participate in RNA processing to downregulate TCA enzyme expression, thereby remodeling the TCA cycle and glycolytic flux is increased to promote tumor proliferation." (PMID 36012594, 2022). "In order to extend the pathway regulated by circSMARCA5 to upstream signals, we investigated the expression of: (i) circSMARCA5, (ii) mRNA of its negative regulator DHX9 (see Discussion), and (iii) Iso8a and Iso8b VEGFA mRNA isoforms in a cohort of 28 GBM tumor biopsies." (PMID 33562358, 2021). "We observed DHX9 and MATR3 (in Tumor A, set 1), HNRNPC and LARP1 (in Tumor A, set 2), SRSF1 (in Tumor B, set 1 & Tumor B, set 2), SRSF6 and IGF2BP2 (Tumor B, set 2), HNRNPU (in Tumor B, set 2 & Tumor C, set 2), and FAM120A and HNRNPA2B1 (in Tumor C, set 2)." (PMID 31892958, 2020). "The other tested DNA sensors (Rig-I, Cgas, Sting, Ddx41, Dhx9, Dhx36, Lrrfip1, Mre11) were expressed in the tumor cells but were not significantly upregulated after irradiation." (PMID 33202881, 2020). "We have observed that DHX9 knockdown results in a cell death response in the majority of tumor cell lines but a growth arrest response in non-transformed cells." (PMID 28427210, 2017). "In the tumour cells, upregulation of AK023948 and DHX9 leads to a high activity of AKT." (PMID 28176758, 2017). "However, we found no significant expression differences of DHX9 between all five tumor clusters in our HGSOC cohort." (PMID 40492347, 2025). "HIF1A-As2 guides its binding protein DHX9 to stimulate MYC signalling, whereas activated MYC, in turn, could transcriptionally activate HIF1A-As2 expression, suggesting HIF1A-As2 and MYC form a double-positive loop that may robustly alter downstream genes and tumor growth." (PMID 37041291, 2023). "Notably, a recent study found that inhibition of DHX9 promoted death of tumor cells but did not affect the function of normal cells at organ level, indicating that DHX9 may have potential to serve as a safe and effective target for CRC therapy." (PMID 31949493, 2020). "siRNA-mediated knockdown experiments indicated that the DExD/H box helicase family, including DHX9 and DDX1–DDX21–DHX36 complexes, was not involved in reovirus-mediated IFN-β induction in the tumor cells other than HepG2 cells." (PMID 25866783, 2015).
infection (14 papers, 2009 to 2024). The state of being infected such as from the introduction of a foreign agent such as serum, vaccine, antigenic substance or organism. "In the RHV and EMCV infection models, we observed a significant difference in ISG production in DHX9-deficient cells." (PMID 36735791, 2023). "The interaction between M029 and DHX9 was also confirmed by coimmunoprecipitation after infection of cells with vMyx-M029V5N." (PMID 33952639, 2021). "This colocalization of DHX9 and M029 was also confirmed after infection of cells with vMyx-M029V5N, a MYXV expressing N terminus V5-tagged M029 under the native viral promoter." (PMID 33952639, 2021). "Complementarily, overexpression of DHX9 resulted in an increased infection burden in A549 cells." (PMID 38940585, 2024). "Apart from MYXV, infection of A549 cells with either VACV or CPXV also caused cytoplasmic localization of DHX9 during the late replication cycle (data not shown)." (PMID 33952639, 2021). "Interestingly, other DEAD-box helicases have also been shown to form complexes with NLR family members: In mice, Nlrp9b uses the DEAD-box protein Dhx9 as a sensor for double-stranded RNA to induce inflammasome activation and pyroptosis following infection with dsRNA viruses." (PMID 34054816, 2021). "Enhancement of translation but overall reduction in infection with the lack of DHX9 points to this protein having a role during alphaviral infection; however, a specific role as an RBP has not been characterized." (PMID 36680204, 2023). "Additionally, infection with vMyx-M029KO virus, which is highly defective in late protein synthesis in human cells, also significantly reduced DHX9 antiviral granules." (PMID 33952639, 2021).
neurodevelopmental disorder (3 papers, 2024 to 2025). A behavioral and cognitive disorder with onset during the developmental period that involves impaired or aberrant development of intellectual, motor, or social functions. "Heterozygous loss-of-function variants of DHX9 are associated with neurodevelopmental disorders in humans." (PMID 39392462, 2024). "Moreover, we identified heterozygous LOF mutations in DHX9 as potentially causative for a newly characterized neurodevelopmental disorder." (PMID 39177028, 2024).
neurological disorders (2 papers, 2024 to 2025). "Interestingly, monoallelic rare DHX9 variants increase R-loop levels and are shown to be associated with neurological disorders." (PMID 40047526, 2025).
DHX9 also shares sentences with these, for which no sentence is quoted: influenza (6 papers); colon cancer (3); HIV-1 infection (3); breast invasive carcinoma (2); choriocarcinoma (2); Ewing's sarcoma family tumors (2); malaria (2); multiple myeloma (2); prostate neoplasm (2); amyloidosis (1); Arthritis (1); Ataxia (1); atherosclerosis (1); autoimmune disorders (1); bladder urothelial carcinoma (1); Bloom syndrome (1); brain tumor (1); cervical squamous cell carcinoma (1); cholangiocarcinoma (1); coeliac disease (1); colon adenocarcinoma (1); COVID-19 (1); cryptosporidiosis (1); cystic kidney (1); dengue (1); diffuse large B-cell lymphoma (1); embryonal tumor (1); endocervical adenocarcinoma (1); head and neck squamous cell carcinoma (1); hematological diseases (1).
A further 24 diseases each share a sentence with DHX9 in 1 paper.